MAGEA7P (MAGE family member A7, pseudogene)
Synonyms: formerly MAGE7; MAGEA7
Gene: Unprocessed pseudogene on chromosome X (149,808,214 to 149,809,155, forward strand). Ensembl gene ENSG00000224732.
Diseases named in the same sentence as MAGEA7P in open-access papers:
MAGEA7P is named in the same sentence as 2 diseases in open-access papers, as found by Europe PMC text mining. Sharing a sentence is not in itself a finding about the gene and the disease.
MAGEA7P shares sentences with these, for which no sentence is quoted: cancer (1 paper); lung carcinoma (1).